FOXP3 (forkhead box P3)
Diseases named in the same sentence as FOXP3 in open-access papers (continued):
Sharing a sentence is not in itself a finding about the gene and the disease.
tumor (continued). "The tumor-infiltrating CD8+ T cell expression level in RGC was significantly higher following benign initial disease than following malignant initial disease (p=0.046), whereas the tumor-infiltrating expression of CD8, CD4, FoxP3, and CD20 was not directly relevance with RFS." (PMID 36451224, 2022). "However, CTLA-4 expression, on tumor-specific CD8+ T cells and CD4+ Foxp3+ Tregs was not affected by anti-CD73 treatment in this tumor." (PMID 35711418, 2022). "Furthermore, strong positive correlations were found between levels of FoxP3+Helios− Tregs with CD4+TIM-3+ T cells and CD4+LAG-3+ T cells (r = 0.636, p = 0.002; r = 0.502, p = 0.017, respectively) in tumor tissues but not in PBMCs and NILs." (PMID 35455287, 2022). "In addition, to determine how the lack of IGF1R in the lung TME is conditioning tumor growth and metastasis, we performed double fluorescence immunostainings of p-IGF1R with CD68 (TAMs) and FOXP3 (FOXP3+ TILs) in lung sections from LLC-challenged mice." (PMID 35688943, 2022). "Unlike FOXP3+ Tregs, the frequency of CD123+ pDCs was lower in most CRC tumor tissues." (PMID 35619702, 2022). "Although studies have shown that the high infiltration of FOXP3+Helios− Tregs and TNFRSF9+ Tregs in tumors are not conducive to the prognosis of patients, the function and mechanisms of these subtypes of Tregs in tumor‐related immune suppression need to be further investigated." (PMID 35474948, 2022). "Tretinoin is also a powerful regulator of Treg activity and can induce Foxp3 expression in peripheral CD4+ T cells, converting them to Tregs as well as increase the number of tumour infiltrating Tregs, although we saw no changes to CD4+ Treg and non-Treg populations." (PMID 35402250, 2022). "Moreover, strong positive correlations were observed between levels of FoxP3+Helios+ Tregs with CD4+TIM-3+ T cells and CD4+LAG-3+ T cells (r = 0.767, p < 0.0001; r = 0.749, p < 0.0001, respectively) in tumor tissues but not in circulation or normal tissues." (PMID 35455287, 2022). "DEN-induced HCC tumours in ROCK1nc mice displayed higher grade steatosis, which was accompanied by significantly more neutrophils and CD8+ T cells relative to ROCK1wt mice, while levels of Foxp3+ regulatory T cells (Tregs) were not different." (PMID 36497425, 2022). "Assuming a pro-cancer role for Tregs and an anti-cancer role for CD8+ T cells, such an event is possible only if the two lymphocytes infiltrate simultaneously into the tumor, where the positive effect of CD8+ T cells overweighs the negative effect of FoxP3+ T cells on cancer prognosis." (PMID 35634289, 2022). "However, FoxP3 and CTLA-4 in tumor stroma appeared to have no prognostic effect within the study population." (PMID 34095135, 2021). "Interestingly, tumor preconditioning and the TME were essential for GITR dependent modulation of Foxp3 expression since Treg cells not exposed to the TME did not lose Foxp3 expression following treatment with DTA-1." (PMID 34539668, 2021). "However, among the tumor-infiltrating lymphocytes, CD3, CD4, and CD8 had prognostic implications, but not FOXP3 and immune cell score." (PMID 34898543, 2021). "To prove that LB100 sensitised tumour cells to ICB therapies regardless of its Treg inhibitory activity, we showed the expression of p110δ in Treg (Foxp3+), but not in CD8+ or polymorphonuclear myeloid-derived suppressor cell (PMN-MDSC) (Ly6Ghigh) in the CT26 tumour microenvironment." (PMID 34911954, 2021). "However, the strong positive correlation of FOXP3+ cells to other infiltrating immune cells, including CD8+ cytotoxic T cells, suggests that SIR is not likely to be the result of a strong local anti-tumor immune response in CRC." (PMID 32316975, 2020).
tumor (continued). "Our results indicated that 70% of γδT cells in uterus expressed CD25 but did not express Foxp3, indicating CD25+γδT cells in uterus were not Foxp3+γδ Treg cells which were regulatory γδT cells and reported to be present in human PBMC and tumor infiltrating leukocytes(TIL)." (PMID 33519808, 2020). "The representative images of FOXP3+Tregs (a) CD163+M2 macrophages (b); the representative positive expression of PD-L1 in tumor tissues (c); the representative negative expression of PD-L1 in tumor tissues (d); CD3+T lympmcytes (e); CD8+T lympmcytes (f)." (PMID 31174544, 2019). "Finally, we found that the densities of CD3 + and CD8 + cells were higher in MSI-H tumours than in MSS tumours, but that the densities of CD4 + and FOXP3 + cells were not affected by the MSI status of the tumour." (PMID 31488881, 2019). "Of note, (R)-crizotinib, alone or in combination with CDDP, increased the infiltration of Kras-induced NSCLC by CD8+ cytotoxic T lymphocytes (CTL), yet had no major effect on the local frequency of Foxp3+ regulatory T cells (Treg), meaning that it improved the CD8/Foxp3 ratio in the tumor bed." (PMID 30940805, 2019). "The tumor was negative for PD-L1, with low levels of infiltrating T lymphocytes while demonstrating relatively higher numbers of 4-1BB/CD137+ cells and an elevated CD8/FoxP3 ratio." (PMID 31801624, 2019). "D-TILs was here defined as numbers of CD4+ cells, with and without FOXP3, and CD8+ lymphocytes per mm2 of tumor determined through 180 multispectral, multicolor immunofluorescence (IF) image cubes (×200 magnification; median of 3 images per case; n = 51 selected CRPC biopsies)." (PMID 30179225, 2018). "However, the densities of tumour infiltrating CD3+, CD8+, FoxP3+ T cells, CD68+ macrophages and neutrophils did not significantly correlate with serum MMP-8 levels, when the correlations were adjusted for tumour stage, patient age and patient gender." (PMID 29808017, 2018). "Alternatively, but not exclusively, FOXP3+ T cells may have high-affinity TCRs to self-MHC and/or tumor antigens and be more prone to activation." (PMID 30061879, 2018). "Furthermore, immunological staining of FOXP3, CD4 and CD8 showed no marked difference in immune cell infiltrate in tumor environment following treatment." (PMID 29492202, 2018). "Treatment with the mPD1-Fc-OX40L ARC led to an increase in CD4+ T cell populations in both the tumor and spleen, that were enriched for effector T cells (CD4+CD25−) compared with non-effector/Treg (CD4+CD25+ or CD4+FOXP3+) cells." (PMID 30563566, 2018). "E-cadherin levels showed a correlation with high CD8 TN/STR (rank Spearman p=0.0435) and from this it was noted that those cells with low levels of E-cadherin had significantly lower numbers of CD8, FoxP3, and CD68 cells in the tumour nest but not in the stroma and hence lower TN/STR ratios." (PMID 29416729, 2018). "A negative correlation between tumor size and the abundance of both CD3+ (r2 = –0.87, p < 0.0001), CD8+ (r2 = –0.84, p < 0.0001), CD4+ (r2 = –0.85, p < 0.0001) and FOXP3+ (r2 = –0.88, p < 0.0001) cells was observed." (PMID 30687269, 2018). "Additionally, we showed the systemic role of T-cells in tumor protection through a negative correlation between tumor size and T-cells subpopulations and an increasement of BL23-specific local Foxp3 levels in tumor-bearing mice." (PMID 30687269, 2018). "For example, inhibition of the “do not eat-me” CD47-SIRPα interaction between tumor cells and phagocytic macrophages leads to an anti-tumor immune response characterized by the presence of CD8+ cytotoxic T lymphocytes and absence of FOXP3+ immunosuppressive T regulatory cells." (PMID 30187085, 2018). "In addition, the therapeutic outcomes in M3-9-M tumor models correlated with the increased incidence of CD4+ and CD8+ T cells but not with the CD4+CD25+Foxp3+ regulatory T cell populations in the tumor." (PMID 28539588, 2017).
tumor (continued). "Tumor xenograft model further confirmed that about 50,000 HT29 cells could form tumors in nude mice, while the same number of HT29 cells with FOXP3 transfection could not form detectable tumors." (PMID 28591725, 2017). "In conclusion, our retrospective study comprising 89 CRC patients with stages IIA, IIIB, and IIIC confirms that infiltration of the tumor stroma by CD68+/iNOS− TAMs and CD8+/FoxP3+ Tregs is a negative prognostic factor and there is a positive correlation between these types of infiltration." (PMID 28343267, 2017). "To evaluate the potential role of Tregs and its subsets in human GC, we first gated CD4+CD25+Foxp3+ T lymphocytes as Tregs and analyzed the Treg percentage within the total CD4+ T-cell populations from peripheral blood, non-tumor, peritumoral, and tumor tissues of GC patients." (PMID 28817117, 2017). "We show a decreased ratio of IFNγ+ to FOXP3+ cells in CD4+ TILs lacking HIF-1α, which could further contribute to the observed accelerated tumor growth." (PMID 29136509, 2017). "CCR2+ T cells were nearly absent in FoxP3+CD4+ T cell fractions, indicating that HNSCC-circulating aTreg cells may be recruited to the tumor microenvironment by endogenous MCP-1 via binding to CCR4 but not CCR2." (PMID 27177223, 2016). "Furthermore, these levels of both CD4+CD25+ and CD25+Foxp3+ cells in (rapamycin + SK-TCL-mDC)-treated mice were quite comparable to the levels detected in normal (i.e., not tumor-bearing) mice (i.e., 3.4% and 0.4%, respectively)." (PMID 26426423, 2015). "Interestingly, even after tumor challenge, the expression levels of total CTLA-4 in CD44hiCD8+ T cells, and the percentages of CD4+Foxp3+ Tregs in lung tumors, spleens, or lymph nodes were not reduced in the immunized SKAP55−/− mice (Fig4F)." (PMID 25851535, 2015). "Importantly, differences in the tissue location of effector T cell and Treg infiltration within tumor epithelial vs stromal compartments may influence their function and prognostic impact, yet studies have not adequately addressed this issue, especially for FoxP3+ Tregs." (PMID 22879926, 2012). "These in vivo studies suggested that naïve Foxp3-negative CD8 and CD4 T cells could not be induced to express Foxp3 after they have infiltrated and been exposed to signals within the tumor microenvironment." (PMID 22112546, 2011). "We finally asked if Foxp3-negative CD4 or CD8 T cells, adoptively transferred into tumor-bearing mice, could be induced to express this transcription factor." (PMID 22112546, 2011). "Preliminary experiments showed that supernatants from tumours treated with any of the drugs had no direct effect on the numbers and/or activation states of NKs (CD3−, CD69+, CD56+ and CD16+), T cells (CD3+, CD25+ and CD69+) and T-regs (CD4+, CD25+ and Foxp3+)." (PMID 19997099, 2010). "Additionally, in JAKi-treated KPCSmad4-KO PDAC, macrophages, apCAFs and FOXP3+ T regulatory T cells were reduced, and non-exhausted total T cells and CD8+ T cells were increased, which may contribute to impairing tumor growth." (PMID 39841099, 2025). "IHC was used to stain tumor tissues; however, because of the absence of some samples, ICOS levels were only determined in 47 patients, PD‐L1 levels were only measured in 62 patients, CD163 levels were only determined in 67 patients, and FOXP3 levels were only determined in 66 patients." (PMID 38616999, 2024). "Immunophenotyping shows that the frequency of tumor-infiltrating Tregs was not increased in Foxo1fl/flCD4Cre+ mice in comparison to Foxo1fl/flCD4Cre− mice with Zn supplementation, suggesting that FOXO1 is essential for Zn-mediated Foxp3 Treg function in promoting tumor growth." (PMID 39247196, 2024). "The fact that FOXP3+ TILs, in contrast to CD8+ and CD4+ TILs, did not decrease in inner tumor areas further suggests that regulatory T-cells may better survive in the microenvironment of the tumor body." (PMID 36586079, 2023).
tumor (continued). "In normoxic tumor tissues, the infiltration of CD4+ T cells, CD8+ T cells, and CD11c+ dendritic cells was more significant in the combined treatment group than the IR alone group, while the infiltration of FoxP3+ regulatory T cells showed no significant changes." (PMID 36238646, 2022). "Moreover, strong negative correlations were found between frequencies of FoxP3-Helios- non-Tregs and CD4+TIM-3+ T cells in TILs, and they were found to be stronger in advanced tumor stages compared to early stages (r = −0.751, p = 0.019 [early]; r = −0.812, p = 0.0007 [advanced])." (PMID 36146549, 2022). "Analyzing the phenotypical characteristics of CD4+ T cells infiltrating tumor and normal tissue, it was found that independent of the pathologic response, there was an increase in the frequency of Tregs, characterized by expression of the IL-2 receptor α chain (CD25) and FoxP3 transcription factor." (PMID 35562400, 2022). "Depleting FOXP3 (hi) Treg cells from tumor tissues could be deployed to increase the antitumor immunity to treat CRC or other cancers, whereas other strategies enhancing the levels of FOXP3(lo) non-Treg T cells could also be used to suppress or prevent tumorigenesis." (PMID 33809974, 2021). "Additionally, compared to the nontumoral mucosa and peripheral blood of CRC patients, the tumor tissue was characterized by significant accumulation of Helioshigh Tregs, high levels of TSDR demethylation at the FOXP3 locus, and high levels of OX40 and CD39 expression." (PMID 34257746, 2021). "Therefore, there may be two functionally distinct populations of FOXP3-positive CD4+ T cells in CRC, the suppression-competent FOXP3high Treg cells, and the non-suppressive FOXP3low T cells that prevent tumor formation via antitumor immunity." (PMID 33668122, 2021). "Notably, GFP+Foxp3+CD4+ T cells were barely detected in tumor, while a substantial population of Tfr was observed in dLNs, suggesting the absence of Tfr population in tumor mass." (PMID 32477338, 2020). "Thus, after inoculation with human commensal microbes of responder patients in mice, the tumor microenvironment showed an increase of SIY-specific CD8+ T cells, but not of FoxP3+CD4+ regulatory T cells which lead to an increased priming of tumor antigen–specific CD8+ T cells." (PMID 31067796, 2019). "Thus, although SM16 administration resulted in significantly inhibited tumor growth and concomitant increase in the CD4+CD25−FoxP3+ Treg-like subpopulation, it did not significantly increase the CD4+CD25+FoxP3+ Treg subpopulation in the spleen, lymph nodes or tumor microenvironment of TBM." (PMID 31288845, 2019). "In addition, a subset of the responding CD4+ T cells expressed forkhead box protein P3 (FoxP3), indicating that although a regulatory component of the vaccine-activated CD4+ T cell response was induced, the anti-tumor vaccine response was not limited by these regulatory CD4+ T cells." (PMID 30956760, 2019). "As determined by flow cytometry, α-PD-1 monotherapy did not significantly affect tumor infiltration of total CD4+ or CD8+ T cells but, unexpectedly, it consistently and significantly skewed the balance between CD4 + CD25 + Foxp3+ Tregs and CD4 + Foxp3- Th cells." (PMID 30832732, 2019). "In summary, TAM homeostasis within the MC38 tumor microenvironment is maintained by production of CSF1, not IL34, and inhibition of signaling not only influenced the myeloid compartment but also inhibited CD4+ T cell accumulation, favoring a reduction in CD4+ FoxP3+ T cells." (PMID 31552020, 2019). "The overall proportion of T cells in the tumor had no significant increase (CD3+); however, encouragingly, the number of both CD4+ and CD8+ T cells increased, while that of Treg population (CD4+Foxp3+) decreased, reflecting an activation of the adaptive immune response." (PMID 31118418, 2019).
tumor (continued). "Increased number of CD8+ cells in OSCCBP group, lack of correlation of PD-L1 with number of Foxp3+ cells and negative correlation between number of CD8+ cells and immunoexpression of PD-L1 seem to be consistent and suggest that tumor infiltrating CD8+ cells may have other than suppressive function." (PMID 28669079, 2018). "Some of the tumor infiltrating cells, e.g. CD4+, CD335+ cells were increased in the tumors of all responders mice, irrespective of which virus was employed, whereas CD8+, Foxp3+, CD141+ were increased and CD11b+ cells were decreased preferentially in R-115-treated mice." (PMID 30080893, 2018). "In order to do justice to their contributions in tumor settings, other Foxp3 non-expressing, peripherally induced CD4+ regulatory cells, specifically Tr1 cells, will be discussed separately as such in one section and the rest of our discussion will focus on Foxp3+ peripherally converted iTregs." (PMID 23874336, 2013). "However, determining the density of CD8+ or FOXP3+ TILs in clinical settings requires the evaluation of tumor tissue with substantial time and effort and is not cost-effective, whereas peripheral blood NLR can be easily determined using preoperative laboratory data without the need for tumor tissue." (PMID 38704243, 2024). "While we cannot definitively confirm all the FOXP3+ cells are regulatory T cells, we can conclude that the environment within the cSCC tissues is immunosuppressive compared to ANT and may be indicative of a reduced immune response that would favor tumor growth, regardless of cell lineage." (PMID 35223500, 2022). "Furthermore, we recently found that the frequency of CD4+ T cells expressing Foxp3 was significantly decreased in the tumor but not in the spleen after HSCT and that the decrease in Tregs was dependent on interleukin‐6 (IL‐6) produced by dendritic cells in the tumor." (PMID 26589884, 2016).